CDC25C (cell division cycle 25C)
Diseases named in the same sentence as CDC25C in open-access papers (continued):
Sharing a sentence is not in itself a finding about the gene and the disease.
tumor (continued). "The OE-KIF22 group mice had heavier weight and bigger volume of tumor, and IHC results suggested that KIF22, CDC25C, CD38, and Ki-67 were strongly stained in the OE-KIF22 group." (PMID 38713252, 2024). "Results from our analysis also indicate that, among the thirty genes which are differentially expressed in OSCCs, seven of them (namely BRCA1, CCNE2, CDC25C, CDK1, CDK2, E2F1, and FANCD2) positively correlate with both tumor grade and HPV infection." (PMID 36768994, 2023). "Second, our study is also the first to test the link between CDC25C protein expression levels in early-stage LUAD and tumor size." (PMID 36830899, 2023). "We contemplate that the concordance between the expression of CDC25C mRNA in LUAD and the expression of CDC25C protein in LUAD suggests that associations between CDC25C mRNA levels in LUAD and clinical outcomes could also be detected by quantifying CDC25C protein level in the tumor." (PMID 36830899, 2023). "Among these genes, CDC25C, NEIL3, H2AFX, NBN, XRCC5 and RAD1 were all validated to be upregulated in NSCLC tumor tissues." (PMID 36408135, 2022). "Among these genes, PLK1, CDC25C, ESCO2, AXIN2, TREX2, ALKBH2, and MC1R were upregulated in tumor tissues, whereas IGF1 and ESR1 presented downregulation." (PMID 35484177, 2022). "Although the nature of the interaction between TOPK, CHK1 and Cdc25C remains elusive, our observations strongly support a model in which upregulation of TOPK in tumour cells plays a vital function during the increased cellular demands of replication." (PMID 33168956, 2021). "Western blot analyses further indicated that treatment with 75 mg/kg ribociclib alone only partially suppress cell cycle proteins such as Cdc25C, cyclin B1 and p‐Cdc2 in HCC21‐0208 tumour." (PMID 33179425, 2021). "Here, we examined the expressions of p‐CDC25C, CDC25C, p‐CDK1, CDK1, and cyclinB1 in tumor tissues from mice with different treatments by western bolt." (PMID 32780562, 2020). "Taken together, our data indicated that SL4 retarded tumor growth in vivo by decreasing the expression level of PCNA and cdc25C, and increasing the expression of p21." (PMID 27819344, 2016). "Hsa-miR-16, mentioned previously to be anti-correlated in tumours with several potential mRNA targets including E2F3, C8ORF30A, and SCAMP5, is significantly positively correlated with CDC25C." (PMID 22452920, 2012). "CDC25C and CDC45 are closely related to tumor development and tumorigenesis." (PMID 38725628, 2024). "Another study found decreased expression of cyclin B1, CDC2, p-CDC2, and CDC25C, which may be due to SFN-induced upregulation of the tumor-suppressor gene Egr1 in various breast cancer cells." (PMID 34638282, 2021). "Taken together, these results indicated that METTL8 expression was enhanced in LSCC, which could promote tumor growth dependent on PCNA, c-myc, and Cdc25c." (PMID 33816462, 2021). "Hence, the expression of CCNB1, CDC25C, and CHEK2 played an important role in the carcinogenicity and tumor progression of NSCLC." (PMID 34504528, 2021). "Overexpression of CDC25C may be related to the activation of the cyclin B1/CDK1 complex and promote the growth of the corresponding tumor, and there is a correlation between survival and proliferation rate." (PMID 32518522, 2020). "This means that when the expression level of CCNB1, CDC25C, CDK1 and PLK1 is reduced, the abilities in tumor cells proliferation could be inhibited at the same time." (PMID 29500418, 2018). "Mice given doxycycline in the drinking water developed smaller tumors than mice that were not given doxycycline, suggesting that cdc25C-S216A expression leads to a decrease in tumor formation." (PMID 27253419, 2016). "In contrast, suppression of CDC25C in 277 cells had no measurable effect on the frequencies of tumor cell subpopulations." (PMID 27775025, 2016).
tumor (continued). "The results suggested that HAR abrogated tumor cell proliferation through inducing G2/M cell cycle arrest by increasing cyclin-dependent kinase inhibitor (CDKI)-p21 levels and modulating the activity of Cdc25C/Cdc2 in vitro and in vivo." (PMID 26678950, 2015). "Meanwhile, we observed a significant overlap in the expression patterns of key cell cycle regulators, including CDC25C, CCNB1, and CDK1, with PPIH in malignant cells, further suggesting that PPIH may promote tumor cell proliferation by modulating cell cycle progression." (PMID 40895540, 2025). "A salient translational finding is that patients with detectable triple positive BTCs and/or overexpression of CDC25C might benefit from the addition of platinum-based chemotherapy treatment, independent of their tumor or nodal staging." (PMID 27775025, 2016). "According to the analyses between phospho-CDC25C (Ser 216) and clinical parameters, high expression of phospho-CDC25C (Ser 216) in cytoplasm/nucleus was significantly correlated with advanced FIGO stage, large tumor diameter and deep invasion as well as poor disease-specific survival." (PMID 20500813, 2010). "In particular, we show that CDC25C expression in LUAD is mainly restricted to tumor cells, whereas areas of inflammation inside the tumor and tumor-adjacent lung parenchyma nearly do not stain for CDC25C." (PMID 36830899, 2023). "Immunohistochemistry and immunofluorescence analysis showed that CDC25C, H2AFX, NBN, XRCC5 and RAD1 had positive strong expression in NSCLC tumor tissues and negative weak staining in normal lung tissues and mainly distributed in nucleus and cytoplasm." (PMID 36408135, 2022). "High levels of CDC25C are advanced events in tumor development, as evidenced by the overexpression of CDC25C and the late FIGO stage, the presence or absence of lymph node metastasis, tumor size, and degree of differentiation." (PMID 32518522, 2020).
infection (9 papers, 2008 to 2021). The state of being infected such as from the introduction of a foreign agent such as serum, vaccine, antigenic substance or organism. "PRRSV-infected cells showed increased levels of the Ser216-phosphorylated form of Cdc25C compared with those in mock-infected controls at 24 and 48 h post-infection." (PMID 30400903, 2018). "RT-PCR analysis performed 24 hours post infection with an adenovirus vector expressing DN-NF-YA (Ad-DN-NF-YA) shows that cyclin A2, B2, cdk1, cdc25C, topoisomerase IIα mRNAs were greatly down-regulated (lane 3)." (PMID 18431504, 2008). "Interestingly, transcript levels of genes regulating DNA replication and cell cycle progression (Cdc25c, Fosb, Cdkn3, cyclin E2, Chaf1b, Cdt1) were specifically increased in SkMCs and neurons after infection." (PMID 28775382, 2017). "Chk2 has also been shown to phosphorylate CDC25C in vitro; however, our data suggest that Chk2 activity is unable to sustain a permanent G2 arrest during MVM infection." (PMID 24415942, 2014). "Our result showed that infection of HPV correlated with high expression of CDC25B and nuclear phospho-CDC25C (Ser216)." (PMID 20500813, 2010). "Similarly, the infection of human herpesviruses is known to induce cell cycle arrest by enhancing the CDK1 phosphorylation either through perturbing the activities of Wee1 and CDC25C phosphatase or through inactivating the cyclin B-CDK1 complex." (PMID 34756071, 2021). "Although increase of Cdc25C expression in PRRSV-infected cells was not obvious at 48 h, the Ser216-phosphorylated form of Cdc25C in PRRSV-infected cells showed remarkable increase compared with those in mock-infected controls at 24 and 48 h post-infection." (PMID 30400903, 2018).
hematologic malignancies (2 papers, 2019 to 2023). "The increase expression of p21 and the reduction of cdc25c suggested an arrest at early G2 entry for both sensitive and resistant cells, results observed in other studies hematologic malignancies." (PMID 31470872, 2019).
CDC25C also shares sentences with these, for which no sentence is quoted: adenocarcinoma (2 papers); epidermoid carcinoma (2); Insulin resistance (2); nasopharyngeal carcinoma (2); pancreatic adenocarcinoma (2); platelet disorders (2); aggressive (1); AIDS (1); B-cell neoplasm (1); Burkitt lymphoma (1); colorectal adenoma (1); dental caries (1); diabetes mellitus (1); endometrium carcinomas (1); Fanconi anemia (1); hypertrophic cardiomyopathy (1); kidney chromophobe (1); liver (1); lung squamous cell carcinoma (1); lymph node metastases (1); marginal zone lymphoma (1); medulloblastoma (1); Myelodysplasia (1); Obesity (1); ovarian serous cystadenocarcinoma (1); Penile Squamous Cell Carcinoma (1); pheochromocytoma (1); rectum cancer (1); retinoblastoma (1); sarcoma (1).
A further 6 diseases each share a sentence with CDC25C in 1 paper.